ELN (elastin)
Diseases named in the same sentence as ELN in open-access papers (continued):
Sharing a sentence is not in itself a finding about the gene and the disease.
atherosclerosis (113 papers, 2010 to 2026). A disease characterized by the build-up of fatty material and calcium deposition in the arterial wall resulting in partial or complete occlusion of the arterial lumen. "Results from other studies examining role in desmosine in various diseases suggest that desmosine predominantly reflects elastin degradation in the vascular tissue of the vascular system, likely to be caused by vascular tissue inflammation or atherosclerosis." (PMID 40142864, 2025). "In particular, MMP-1, MMP-2, MMP-3, MMP-7, MMP-9 and MMP-12 have been demonstrated to bind to and to digest insoluble elastin, their activation being associated with cardiac valve diseases, atherosclerosis, aortic aneurysms, and restenosis." (PMID 40926897, 2025). "The decrease in strain is due to the change in the collagen/elastin ratio associated with atherosclerosis, so increasing this ratio decreases the arterial strain." (PMID 36771780, 2023). "With aging, structural changes in arteries such as elastin fragmentation, collagen accumulation, medial vascular smooth muscle cell loss, and atherosclerosis have been reported." (PMID 37745109, 2023). "Pathologic groups presented an arterial strain value smaller than that obtained in the healthy group due to the increase in arterial wall thickness and the collagen/elastin ratio change associated with atherosclerosis." (PMID 36771780, 2023). "Because we used atherosclerosis-prone Apoetm1Unc/J mice that were fed a high-fat diet to intentionally accelerate atherogenesis, we cannot separate changes in elastin fibers associated with aging from those associated with atherogenesis in this mouse model." (PMID 37560112, 2023). "Others reported that impaired elastin structure of the vessel wall was associated with the progression of atherosclerosis in ApoE−/− C1039G+/− crossbred mice compared to ApoE−/− mice." (PMID 37560112, 2023). "Observations from these studies suggest that pDES predominantly reflects elastin degradation in the vascular tissue of the cardiovascular system, likely to be caused by vascular tissue inflammation and atherosclerosis." (PMID 36479574, 2022). "Furthermore, alteration of the microstructural components of the arterial wall, such as elastin degradation and density decrement, have been directly associated with atherosclerosis and hypertension." (PMID 40309506, 2025). "Oxidative stress caused by high iron leads to elastin's destruction and promotes atherosclerosis." (PMID 37132140, 2024). "The elastin is particularly susceptible to proteolytic degradation in atherosclerosis." (PMID 39596083, 2024). "Arterial stiffness and cIMT progression have different and overlapping mechanisms in vascular aging processes, while the former may be related to elastin loss and fragmentation, and the latter relates to atherosclerosis." (PMID 36241708, 2023). "Reduced elastin levels are associated with various diseases such as atherosclerosis and arthritis." (PMID 30071607, 2018). "Both vascular calcification and elastin fibres degeneration cause arterial stiffening which may increase risk of vessel wall damage and result in atherosclerosis." (PMID 27756244, 2016). "High concentrations of silicon are found in normal healthy connective tissues, including the aorta, where it is associated with the elastin and collagen components of the aortic wall, and concentrations decrease with aging and with the progression of atherosclerosis." (PMID 25972522, 2015). "Some studies have shown that elastin may play a key role in tissue calcification and some calcification-related diseases such as atherosclerosis and heart valves calcification have been found associated with elastin degradation." (PMID 26816627, 2014). "In the early phases of atherosclerosis, MMPs facilitate the migration of monocytes, macrophages and smooth muscle cells while at the later stages MMPs can cause degradation of extracellular matrix proteins such as elastin and collagen." (PMID 24232739, 2013).
atherosclerosis (continued). "Moreover, aging may result in calcium accumulation (a measure of atherosclerosis) and increased aortic diameter (a possible measure of elastin loss), which may contribute to a downward shift of the aorta." (PMID 37999761, 2024). "Moreover, HT is suggested to be linked with a marker of atherosclerosis, namely the pulse wave velocity, a correlation that leads to arterial stiffness with structural changes such as thinning and fragmentation of elastin, medial smooth muscle cell necrosis, and fibrosis." (PMID 37755241, 2023). "Interestingly, nonatherosclerotic aging phenotypes are usually described as degenerative changes in the arterial wall consisting of elastin loss and fragmentation of the internal elastic lamina, some of which may also overlap with atherosclerosis." (PMID 34374904, 2022). "The incidence of atherosclerosis increases with age, and patients with psoriasis are also at higher risk of developing atherosclerosis, which is accompanied by increased and dysregulated elastogenesis leading to a disproportionate increase in elastin accumulation." (PMID 35625870, 2022). "However, the 4-HNE-induced alteration of skin elastin production associated with the pathophysiology of skin aging appeared to be different from the age-associated changes in the case of atherosclerosis, which is also considered chronic inflammatory vascular disease." (PMID 33920659, 2021). "Furthermore, differences in the prevalence of atherosclerosis risk factors as well as differences in pathological changes such as vessel thickening, elastin loss, and concentric intimal thickening between anterior and posterior circulation have been demonstrated only recently." (PMID 29672624, 2018). "Calcification in blood vessels occurs in the intima (in the context of atherosclerosis and in association with lipids, macrophages and VSMC), and in the media (involving elastin and VSMC)." (PMID 40926897, 2025). "On the other hand, mechanical stress induced by hypertension destroys elastin, promotes collagen deposition and fibrosis, leading to a gradual increase in atherosclerosis." (PMID 40034990, 2025). "The crucial role of RSV in atherosclerosis is also due to its anti-inflammatory properties; in fact, it acts by preventing the damage to elastin fibers induced by TNF-α—induced in aortic tissue." (PMID 41228388, 2025). "In the current study, we demonstrated the feasibility of molecular MRI using an elastin-specific probe to visualize and evaluate an IL-1β targeted anti-inflammatory therapy against atherosclerosis in a murine model." (PMID 39232217, 2024). "Potential mechanisms for the enlargement of PVS include atherosclerosis, arteriolosclerosis, and elastin dysfunction, which reduces the pliability and increases pulsatility." (PMID 38811657, 2024). "Collagens, fibronectin, laminin, elastin, and proteoglycans are crucial proteins during atherosclerosis development." (PMID 39596083, 2024). "As atherosclerosis progresses, calcium and lipid deposition on elastin makes it more prone to proteolytic degradation." (PMID 39401163, 2024). "Taken together, these results suggest that with progressing atherosclerosis, an increase in local IL-1β and decrease in elastin occurs." (PMID 39232217, 2024). "Throughout the progression of atherosclerosis, cysteine proteases play a significant role in the remodeling of extracellular matrix proteins, ultimately impacting the composition of elastin and collagen." (PMID 39420987, 2024). "Human abdominal aortic aneurysms (AAAs) are characterized by increased activity of matrix metalloproteinases (MMP), including MMP-12, alongside macrophage accumulation and elastin degradation, in conjunction with superimposed atherosclerosis." (PMID 38891996, 2024).
atherosclerosis (continued). "In this complex, NEU-1 is essential for elastogenesis, signal transduction through this receptor and for biological effects of the elastin-derived peptides on atherosclerosis, thrombosis, insulin resistance, nonalcoholic steatohepatitis, and cancers." (PMID 38663826, 2024). "To conclude, we demonstrated that 01BSUR hinders the progression of atherosclerosis by reducing plaque size, inflammatory markers, and elastin content." (PMID 39232217, 2024). "Authors have found that elastin lamellae become less stiff as atherosclerosis develops (reduction of 18.6%), and the stiffness of interlamellar zones increases significantly with the formation and development of atherosclerotic plaques (50%)." (PMID 36771780, 2023). "We performed this study to examine how grayscale ultrasound texture features and elastin fibers change in plaque-free segments of the arterial wall in a murine model prone to atherosclerosis." (PMID 37560112, 2023). "Arterial stiffness involves changes in the extracellular matrix, including elastin degradation and collagen deposition, leading to atherosclerosis." (PMID 37260949, 2023). "This study found that elastin and collagen content were significantly higher in the exercise group but only in the early-stage atherosclerosis model." (PMID 35419434, 2022). "Treatment of mice with elastin-derived peptides (EP), elastin decomposition products of vascular aging, induced atherosclerosis in mice via EP’s directly binding the elastin receptor complex (ERC)." (PMID 36009856, 2022). "In a mouse model of atherosclerosis, administration of elastin-derived peptides increased atherosclerotic plaque size formation through a NEU1–PI3K pathway." (PMID 34688655, 2021). "Such monitoring of changes in elastin content and the high abundance of elastin during plaque development, provide a non-invasive tool for assessing plaque burden in atherosclerosis." (PMID 35071257, 2021). "This review article summarizes the role of elastin in myocardial ischemia-reperfusion, atherosclerosis, and atrial fibrillation, with emphasis on the potential molecular regulatory mechanisms." (PMID 34917605, 2021). "Surprisingly, we also detected elevated expression of ELN, which is usually lowered in processes related to atherosclerosis, such as pathological flow." (PMID 34299034, 2021). "Factors for vascular calcification and atherosclerosis include death of vascular smooth muscle cells and their differentiation into osteogenic/chondrogenic cells, degeneration/degradation of elastin, and remodeling of the vascular wall." (PMID 31945100, 2020). "The degradation of elastin can generate bioactive fragments called elastokines that contribute to the progression of atherosclerosis, including vascular calcification." (PMID 31273243, 2019). "Proteolytic degradation of elastin in the vascular system promotes the development of atherosclerosis, including blood vessel calcification." (PMID 31273243, 2019). "First, TLR4 can induce the proliferation of vascular smooth muscle cells and upregulate the expression of the elastin-degrading enzyme and cathepsin S that allow smooth muscle cells to migrate to the site of atherosclerosis." (PMID 28002812, 2017). "Collagen and elastin are 2 of the major components of the aortic wall that determine its biomechanic properties and functional integrity, and in atherosclerosis these are broken down." (PMID 25972522, 2015). "NEU1 has been proposed to participate in the elastin degradation during vascular aging and provoke atherosclerosis." (PMID 25887273, 2015). "Aged vessels show a number of characteristic pathological processes (reduced medial VSMC number, increased collagen deposition, fracture of the elastin lamellae, etc), many of which are also seen in atherosclerosis." (PMID 24489705, 2014). "Recently, binding of complement to elastin and collagen in the aortic wall has been demonstrated, suggesting a role of complement in the development aortic stiffness and atherosclerosis." (PMID 23199021, 2012).
atherosclerosis (continued). "The progression of PP with advancing age is largely attributed to progressive central arterial stiffening as a consequence of altered vascular structure and function with disruption of elastin, increased collagen, calcification, and atherosclerosis." (PMID 20478760, 2010). "It has been proposed that a reduced outflow through arterioles due to microvascular changes (e.g., atherosclerosis, arteriolosclerosis, elastin dysfunction) may alter their functioning, resulting in the accumulation of waste products and their enlargement." (PMID 40196179, 2025). "Moreover, studies utilizing mice with MMP-12-deficiency or MMP-12 specific inhibition to assess effects on atherosclerosis have reported reduced medial elastin destruction, implicating a role for MMP-12 in atherosclerotic aneurysm formation." (PMID 38891996, 2024). "We hypothesized that 01BSUR treatment alleviates atherosclerosis and its therapeutic effects can be observed on a molecular level using an elastin-specific MR probe." (PMID 39232217, 2024). "In addition, accumulation and cross-linking of AGEs on long-lived matrix proteins such as collagen and elastin also lead to atherosclerosis and endothelial dysfunction, disrupting extracellular matrix-cell interactions." (PMID 38982516, 2024). "The binding of elastin to lipids (as occurs in atherosclerosis) has been shown to alter elastin chain flexibility as well as impede the interaction between water and elastin - two mechanisms that might be expected to impact ISTM mechanics." (PMID 37046262, 2023). "Nonetheless, elastin has a half-life of over 70 years, and destruction of elastin will contribute to the initiation, development and deterioration of various pathological conditions like atherosclerosis, obstructive pulmonary diseases and cerebral aneurysms." (PMID 38129685, 2023). "The media of aortic wall is characterized by altering layers of elastin and smooth muscle cells (SMCs), along with collagen fibers in both layers, and plays a central role in functional and pathological remodeling such as hypertension and atherosclerosis." (PMID 35606390, 2022). "Moreover, it has been well described to date that products of elastin degradation can contribute to the induction and progression of atherosclerosis." (PMID 34374904, 2022). "During such physiological and pathophysiological conditions as inflammation, atherosclerosis, or aging, elastin is prone to proteolytic degradation and, due to the extremely low turnover rate, its degradation is basically an irreversible and irreparable phenomenon." (PMID 34374904, 2022). "They suggested that other mechanisms such as shifts in the collagen/elastin ratios, besides atherosclerosis might be involved in the pathogenesis of arterial stiffness in SLE." (PMID 34790671, 2021). "Besides that, EDPs, the degradation products of elastin actively participate in the pathogenesis of atherosclerosis such as low-density lipoprotein oxidation and vascular calcification and accelerate the progression of the disease." (PMID 34917605, 2021). "The altered homeostasis between synthesis and proteolysis of ECM proteins contributes to the development of atherosclerosis, and the alteration of elastin amounts, incorrect assembly, elastic fiber modification, and elastin fragments are associated with atherosclerosis." (PMID 34917605, 2021). "As we summarized above elastin can be cleaved by elastinases and MMPs, and the excessive production of elastin fragmentation may have a deleterious effect on atherosclerosis progression." (PMID 34917605, 2021). "Though their causes were not of interest in this study, such heterogeneities are known to be induced by several pathologies, e.g., atherosclerosis (intimal hyperplasia, calcification, fat deposition) or cystic medial necrosis (disruption of elastin and smooth muscle cells)." (PMID 31380360, 2019).
atherosclerosis (continued). "Excessive elastin degradation was observed in cardiovascular diseases, atherosclerosis and abdominal aortic aneurism, kidney diseases, and during aging, as upon reaching adulthood, elastin is not synthesized de novo anymore, and consequently its degradation is irreversible." (PMID 30897858, 2019). "While a number of studies provide evidence that the amount of elastin grows with age and progress of atherosclerosis; nearly as many publications aim at proving a directly opposite hypothesis." (PMID 29305778, 2018). "Elastin degradation by MMP9 also generates elastin peptides, which may impact atherosclerosis and abdominal aortic aneurysms." (PMID 28257481, 2017). "Involvement of the MMP family in extracellular matrix remodeling in atherosclerosis is documented but the role of inflammation-induced MMPs on SMC elastin accumulation is unknown." (PMID 28257481, 2017). "In this group of genes we observed correlation between the cytokine IL10 and ELANE, an elastin protease known to degrade elastic fibers as elastin; indicating that elastin degradation and immune response process are common interacting regulatory mechanisms in atherosclerosis." (PMID 25503069, 2014). "Elastin (ELN) is among the markers of atherosclerosis and neovascularization." (PMID 22065928, 2011). "This may be due to the release of MFAP4 from VSMCs in the medial layer into the circulation, or the increased elastase activity in atherosclerosis, which reduces elastin content in atherosclerotic vessels, leading to decreased MFAP4 synthesis bound to elastin in the ECM." (PMID 40406620, 2025). "Traditionally, elevated blood pressure increases the pulsatile wall stress, thereby promoting elastin degradation and leading to long-term atherosclerosis; however, the opposite may be true that arterial stiffness may contribute to the progress of hypertension." (PMID 38836061, 2024). "Whereas the mucoid extracellular matrix accumulation and degeneration of elastin and collagen weakens the vascular wall and increases the risk for aortic complications, the lack of VSMC differentiation potential likely contributes to reducing the risk for atherosclerosis in the ascending aorta." (PMID 37958625, 2023). "Arterial stiffness and atherosclerosis are the main manifestations of vascular aging, and inflammation is considered to be a common pathological feature in this process, which might break the balance between the breakdown and synthesis of elastin." (PMID 34124202, 2021). "From the results, we speculate that the structural alterations of elastin and elastic fibers occurring in the early stages of atherosclerosis can induce the calcified deposits formed on the base of pre-existing structures with the deposition of unesterified cholesterol." (PMID 34917605, 2021). "However, modulation of plaque elastin content and fragmentation suggest TIMP-3–independent effects of miR-181b inhibition, implying that miR-181b may regulate other targets during atherosclerosis that influence elastin content." (PMID 27756793, 2017). "The influence of vascular elastin levels on atherosclerosis remains unclear." (PMID 28257481, 2017). "Thus, elastin-derived peptide formation might prevent and/or delay atherosclerosis and T2D." (PMID 38017481, 2023). "The level of MMP-12, which can hydrolyze elastin and intercellular matrix proteins, as well as activating MMP-3 and MMP-2, was statistically significantly higher in the group of men with atherosclerosis—2.1 times compared to the control group." (PMID 34205079, 2021). "Targeting elastin, another very important ECM protein involved in atherosclerosis remodeling with a dedicated MR probe, has been shown to reliably report on atherosclerotic plaque burden by magnetic resonance imaging." (PMID 31919465, 2020). "Many previous studies demonstrated that altered expression of collagen and elastin in the ECM of vascular smooth muscle cells in the tunica media leads to increased vascular stiffness and atherosclerosis." (PMID 31708766, 2019).